TUSC2P1 (TUSC2 pseudogene 1)
Synonyms: TUSC2P
Gene: Processed pseudogene on chromosome Y (5,887,504 to 5,888,740, forward strand). Ensembl gene ENSG00000285470.
Diseases named in the same sentence as TUSC2P1 in open-access papers:
TUSC2P1 is named in the same sentence as 7 diseases in open-access papers, as found by Europe PMC text mining. Sharing a sentence is not in itself a finding about the gene and the disease.
TUSC2P1 shares sentences with these, for which no sentence is quoted: tumor (5 papers); breast carcinoma (3); esophageal squamous cell carcinoma (3); cancer (1); esophageal cancer (1); oral cancer (1); prostate tumor (1).